MTOR (mechanistic target of rapamycin kinase)
Diseases named in the same sentence as MTOR in open-access papers (continued):
Sharing a sentence is not in itself a finding about the gene and the disease.
cancer (continued). "We have shown that increased activation of the PI3K/AKT/mTOR signalling axis in samples collected from MBC patients that develop disease progression when treated with a CDK4/6 inhibitor in combination with ET extends beyond cancer cells into the surrounding stroma/immune compartment." (PMID 39322687, 2024). "Furthermore, we conducted a review of the crosstalk between ATP5A1 and mTOR in cancer." (PMID 39430254, 2024). "Furthermore, dual-targeted PI3K and mTOR inhibitors also exert potential roles in cancer therapy." (PMID 38763973, 2024). "It is recommended that studies be conducted in the areas of autophagy suppression, cancer, and genetic stability to develop a comprehensive understanding of the intricate mechanisms behind the interactions between pDNA and tachyplesin in the mTOR and NFκB signaling pathways." (PMID 38691208, 2024). "Many processes are linked to the Wnt, mTOR, and MAPK signaling pathways and many parts of these processes intersect with each other; however, the contribution given by PP2A during normal function gives rise to its importance as a target for therapeutics in cancer treatment." (PMID 38184584, 2024). "Furthermore, mTOR controls the production of biological macromolecules, including lipids, proteins, and nucleotides, which supply the building blocks needed for the proliferation of cancer cells." (PMID 39062182, 2024). "Although the hyperactivation of mTOR‐eIF4E positively reinforced proliferation and metastasis in EBV‐positive GC, it also contributed to the generation of numerous W>F peptides and therefore exposed the fatal drawback of cancer cells, increasing their susceptibility to the immune system." (PMID 38994917, 2024). "RAPGEF3 has been implicated in cancer progression through various downstream signals, e.g. RAPGEF3 promotes cancer cell proliferation and/or suppresses apoptosis via Rap1/Akt/CREB signaling, Rap1/B-Raf/ERK and mTOR signaling or acting synergistically with PDE4 to promote the Cyclin E1-Cnx43 axis." (PMID 39687207, 2024). "Notably, while LKB1/AMPK signaling typically acts as a barrier to tumorigenesis by maintaining energy balance and inhibiting mTOR activity, its dysregulation can also confer survival advantages on cancer cells, particularly in the nutrient-deprived tumor microenvironment." (PMID 39682234, 2024). "The phosphatidylinositol 3-kinase (PI3K)/protein kinase B (AKT)/mammalian target of rapamycin (mTOR) signaling pathway is involved in regulating essential biological processes, such as cell growth, proliferation, apoptosis, and cellular metabolism, and plays an important role in cancer." (PMID 39748950, 2024). "However, activating the mTOR pathway eradicated these persistent cancer cell clones." (PMID 38976168, 2024). "This indicates that ZAG may promote cancer progression through the PI3K/AKT/mTOR signaling pathway." (PMID 39711976, 2024). "This could be explained by the fact that rapamycin-mediated mTOR inhibition and autophagy activation, while reducing the proliferative and metabolic activity of tumor cells, may promote the enrichment of dormant cancer cells that remain viable but exhibit low proliferative and metabolic activity." (PMID 39201776, 2024). "Additionally, the utilization of glutamate may depend on the context of nutritional status and microenvironment of cancer cells, as described in our previous reports on mTOR-dependent regulation of xCT transporters." (PMID 38481314, 2024). "Thus, the pharmacological inhibition of Dyrk1B could be beneficial in cancer therapy targeting mTOR signaling." (PMID 38675189, 2024). "Indeed, inhibition of PI3K/Akt/mTOR abolished the advantages of NOP14 on cancer cell proliferation, colony formation in soft agar, cell migration, and tumor growth in an in vivo NPC xenograft model, consistent with the finding that NOP14 expression is mTOR dependent." (PMID 38272224, 2024).
cancer (continued). "Therefore, the Akt/mTOR/p70S6K pathway is closely related to autophagy and may be a potential target for cancer treatment." (PMID 38668684, 2024). "Moreover, a separate study illustrated that anthocyanin from Lycium ruthenicum Murray inhibited cancer cell proliferation, suppressed migration and invasion, induced apoptosis, and caused G2/M phase cell cycle arrest through the activation of the AMPK/mTOR autophagy pathway." (PMID 39335919, 2024). "Therefore, mTOR signaling has been regarded as a promising target in cancer therapy." (PMID 38791040, 2024). "Furthermore, recent studies suggest that TAC-based IS regimens may also affect cancer progression through mTOR pathway activation." (PMID 38341510, 2024). "In addition, autophagy inhibition leads to moderate upregulation of ATG5, seven redundant protein-enhancing combinations to induce apoptosis, while upregulation of Beclin-3 inhibiting PI1K/AKT/mTOR pathway leads to damaging autophagy in cells and effectively overcame drug resistance to treat cancer." (PMID 39247603, 2024). "In addition, AFP could both activate the PI3K/P-AKT/mTOR cellular pathway and stimulate the cancer cell growth by binding with phosphatase and tensin homolog (PTEN)." (PMID 38408930, 2024). "In addition, in patients with a history of cancer, the physician may consider avoiding the prescription of azathioprine or the use of high-dose mycophenolate and may prefer to prescribe an mTOR inhibitor instead if the patient’s condition is appropriate." (PMID 38468637, 2024). "Furthermore, the development of SsnB analogs or derivatives could enhance bioavailability and specificity, making it a promising candidate for combination therapies targeting PI3K/AKT/mTOR-driven cancers." (PMID 39770406, 2024). "Likewise, SUMO may induce a multicomplex protein assembly that initiates and sustains nutrient-induced mTOR signaling to orchestrate human diseases, such as cancer, neurological disorders, and neurodegenerative diseases." (PMID 38395307, 2024). "Thus, the effects of NPRL2 expression on mTOR may be especially important for cell survival and cell proliferation in the context of various cancers." (PMID 38915098, 2024). "However, on the contrary, another study suggested that the imbalance in the mTOR pathway is associated with cancer, rather than the development of liver steatosis." (PMID 39247820, 2024). "Although targeting mTOR signaling may be expected to exhibit potent antitumor immunomodulatory effects in cancer therapy, one of the critical issues is how rapamycin can be utilized to maximize treatment benefits and improve therapeutic efficacy in novel combinations." (PMID 38791040, 2024). "Furthermore, the PI3K/mTOR pathway plays a key role in cell proliferation, survival, metabolism, and migration and is one of the most commonly dysregulated oncogenic pathways in cancers, including CRC." (PMID 39113885, 2024). "Additionally, mTORC2/AKT signaling activates proliferative cell cycles in cancer cells, leading to tumor development, through the binding of mutated rat sarcoma virus (RAS) proteins to mTOR components of mTORC2 and mitogen-activated protein kinase-associated protein 1 (MAPKAP1)." (PMID 39349424, 2024). "Also, the dysregulation of mTOR pathways has been observed in different types of cancers." (PMID 38338233, 2024). "Given the effects of mTOR on γH2AX and the major roles of mTOR in promoting cancer, understanding the interplay between mTOR and DNA damage responses is important for the interpretation of γH2AX levels in cancerous cells and for developing strategies for cancer therapy." (PMID 38971312, 2024).
cancer (continued). "The inhibition of the PI3K/Akt/mTOR signaling pathway for cancer remains a promising therapy; however, drug resistance poses a major problem in clinical settings resulting in limited efficacy of agents; thus, combination treatments with therapeutic inhibitors may solve the resistance to such agents." (PMID 39410536, 2024). "Moreover, studies utilizing exercise-conditioned serum have revealed that both acute and chronic exercise can influence cancer cell signaling pathways, such as STAT3, Akt, mTOR, and the Hippo tumor suppressor pathway, resulting in reduced cancer cell proliferation and tumor growth." (PMID 39336127, 2024). "In addition, mTOR activity and cancer cell growth were suppressed after SKN103 administration." (PMID 38705513, 2024). "In particular, the PI3K/AKT/mTOR (phosphoinositide 3-kinase/protein kinase B/ mammalian (or mechanistic) target of Rapamycin) was found to be hyperactivated in almost all malignant neoplasms with a prevalence ranging from 40% to 90%, thus rendering it an appealing target for cancer treatment." (PMID 38276004, 2024). "Additionally, it suggests that mTOR inhibition (with rapamycin or its analogs), combined with radiation therapy, could potentially enhance the efficacy of cancer treatment by increasing radiation sensitivity." (PMID 38786722, 2024). "In addition, several studies have shown that lncRNAs are regulators of mTOR signaling in cancers." (PMID 38225540, 2024). "However, mTOR-driven senescence can also confer a selective survival advantage on cancer cells." (PMID 39596005, 2024). "Notably, MAPK and PI3K/AKT/mammalian target of rapamycin (mTOR) signaling have a close relationship, and the complex network they constitute is of great significance in cancer cell proliferation, angiogenesis, metastasis, metabolic changes, and response to anticancer drugs 85-87." (PMID 36632213, 2023). "PI3K/Akt/mTOR signaling pathway has been extensively studied and reported to be one of the principal signaling cascades in normal and malignant tissues; aberrant or hijacked PI3K/Akt/mTOR modulation is associated with cancer development, adaptation, and progression." (PMID 38023152, 2023). "However, AMPK plays different roles in tumorigenesis, enabling metabolic adaptation under specific stress conditions such as hypoxia or glucose deprivation, favouring cancer cells survival but also suppressing cancer cell proliferation and tumour formation mainly via mTOR regulation." (PMID 37217519, 2023). "Therefore, mTOR inhibitors are an important target in many types of cancer." (PMID 36978413, 2023). "Thus, ZYX is aberrantly expressed in HCC and promotes cancer progression via the AKT/mTOR pathway." (PMID 37547758, 2023). "Interestingly, we found that mTOR increased VRK2 expression in cancer cells." (PMID 37653031, 2023). "Therefore, targeting PI3K/AKT/mTOR may be an important approach for cancer prevention and treatment." (PMID 36768278, 2023). "Therefore, targeting NUAK1, or co-targeting it with Akt or mTOR inhibitors, may be effective in cancers with hyperactivated Akt signaling." (PMID 38135881, 2023). "Based on our bioinformatics analysis and experimental validation, we confirmed that ESM1 could accelerate OC carcinogenesis (proliferation, apoptosis, metastasis, and angiogenesis) via the Akt/mTOR pathway, which has been demonstrated to be a significant cancer-promoting signaling pathway." (PMID 36594088, 2023). "Therefore, mTOR signaling has attracted attention as a therapeutic target for various cancers." (PMID 36816969, 2023). "Therefore, to clarify the relationship between LAT1 and anti-cancer drug-induced mTOR activation, Western blotting was used to determine the protein expression of LAT1, mTOR, p-mTOR, p70S6K, and p-p70S6K in LAT1-suppressed CRC cells after treatment with oxaliplatin." (PMID 36768934, 2023).
cancer (continued). "The 4E-binding protein 1 (4EBP1), belonging to a family of eukaryotic initiation factor 4E (eIF4E)-binding proteins, acts as a tumor suppressor by modulation the mammalian target of rapamycin (mTOR) pathway in some cancers, and may have additional oncogenic roles under other circumstances." (PMID 36944636, 2023). "In addition, from the identified pharmacogenomic biomarkers of CVM-1118, treating cancer patients carrying specific mutations that activate signaling pathways downstream of TRAP1, such as mTOR and AKT, is expected to have a greater drug response that can be further tested in future clinical trials." (PMID 37351538, 2023). "Additionally, decreased expression of B7-H3 in breast cancer may reduce glycolytic capacity and increase cancer cell sensitivity to Akt/mTOR inhibitors." (PMID 37110590, 2023). "Furthermore, metformin may exert direct inhibitory effects on cancer cells by targeting the signaling pathway of mammalian target of rapamycin (mTOR) and interfering with protein synthesis." (PMID 38138975, 2023). "The phosphoinositide 3-kinase (PI3K)-Akt-mammalian target of rapamycin (mTOR) signalling pathway coordinates the uptake and utilisation of multiple nutrients, including lipids, glucose, glutamine and nucleotides, facilitating the enhanced growth and proliferation of cancer cells." (PMID 37110858, 2023). "The ability of GAS5 to suppress cancer proliferation is due to its acting as a molecular sponge for miR-21, leading to the de-repression of PTEN, the endogenous target of miR-21, whereas reduced GAS5 expression, which is associated with mTOR activation, suppressed PTEN." (PMID 37175800, 2023). "The main difference between these types of compounds with regard to cancer risk may result from the fact that, unlike calcineurin inhibitors, mTOR inhibitors do not interfere with the intracellular antigen processing and presentation of mDCs." (PMID 37887285, 2023). "In addition, rapamycin and its analogs have been developed as mTOR inhibitors for cancer therapy." (PMID 37940975, 2023). "Alteration of the PI3K/AKT/mTOR signaling pathway by either the mutation or amplification of genes participated in the PI3K pathway, overactivation of RTKs or loss of the tumor suppressor PTEN, has been noticed in several cancer cells, causal to tumor progression as well as metastasis." (PMID 37298616, 2023). "Therefore, careful thoughts are needed to use mTOR inhibitors against different cancer types." (PMID 37779156, 2023). "The PI3K/Akt/mTOR signaling pathway affects the tumor cell cycle, apoptosis, autophagy, and angiogenesis by altering the activity of its downstream effector molecules, and therefore, it may be an effective tool for targeted cancer therapy." (PMID 37063281, 2023). "Therefore, PI3K/AKT/mTOR pathway inhibition is essential in reducing cancer cell viability." (PMID 37705007, 2023). "It was shown that IGF-1 secreted by irradiated CAFs’ binding to IGF-1R on CRC cells activated the AKT/mTOR pathway, causing glucose uptake and lactate release increasing solute carrier family 7 membrane 11 (SLC7A11) expression and promoting glutamine uptake by cancer cells." (PMID 36835075, 2023). "It was demonstrated that knockdown of VEGF expression levels after receiving radiation can activate the NF-kB pathway or PI3K/mTOR signaling pathway, which induces DNA damage in cancer cells and contributes to apoptosis, further increasing the lethality of radiation on cancers." (PMID 37598158, 2023). "Initiating of autophagy-associated apoptosis through AMPK activation and PI3K/AKT/mTOR inhibition, promotes apoptosis by suppressing the PI3K/AKT signaling pathway, hinders proliferation and induces autophagy by increasing LC3II and p62 levels in cancer cell lines." (PMID 38074670, 2023). "Additionally, glutamine regulates the mTOR-SREBP1 signaling pathway in cancer cells." (PMID 37887353, 2023).
cancer (continued). "On the other hand, these miRNAs participated in autophagy, multiple cancer species, various well-known tumor-associated processes, and pathways, such as the cell cycle, cell adhesion, the MAPK pathway, the PI3K-AKT pathway, the FoxO pathway, and the mTOR pathway through other target genes." (PMID 37511974, 2023). "Furthermore, inhibition of the mTOR kinase may increase the expression of PD-L1 on cancer cell surfaces." (PMID 36835469, 2023). "The dysregulation of several important signaling cascades, including inflammation, JAK/STAT pathway, PI3K/Akt/mTOR pathway, MAPK pathway, tumor suppressor gene, Wnt/-catenin, and cell cycle and apoptotic pathways, were reported to be associated with the molecular basis of different cancers." (PMID 37298670, 2023). "The DDR gene signature identified in this study was found to be linked with several cancer related pathways including cell cycle, WNT signaling, mTOR signaling and apoptosis in the high risk group, which may be indicative of the potential mechanisms underlying HCC progression." (PMID 37260986, 2023). "In addition to mediating autophagy, the PI3K/Akt/mTOR signaling pathway affects various physiological and pathological processes, such as cell proliferation, differentiation, inflammation, apoptosis, and cancer." (PMID 36973772, 2023). "Therefore, inhibition of the PI3K/Akt/mTOR pathway disrupts cancer cell proliferation." (PMID 36915376, 2023). "We speculate that this can serve as a rescue mechanism for cancer cells during mTOR-targeted cancer therapy as Rapamycin treatment leads to decreased binding of NM1 and active histone marks around transcription start sites of mitochondrial transcription factors similar to NM1 KO cells." (PMID 37816864, 2023). "Moreover, mTORC2 increases cell proliferation and survival through regulation of protein kinases, including AKT, which provides significant motivation for further studies on therapeutic targeting of mTOR complexes in cancer, as mTOR plays an important role in tumor progression." (PMID 37397394, 2023). "The Akt/PI3K/mTOR axis, which is among the vital downstream signaling pathways in cancer promotion, may be a promising find towards cancer therapy, even after EGFR activation, through involvement of a number of natural flavonoids and polyphenolic compounds, including curcumin." (PMID 36982245, 2023). "Therefore, inhibition of SRPK2 or dual inhibition of mTOR and O‐GlcNAc could be promising to suppress the growth of cancer cells dependent on upregulated lipid metabolism." (PMID 37607329, 2023). "In addition, a rise in glutathione expression promotes antioxidant mechanisms and several oncogenic pathways, such as the PI3K/Akt/mTOR and NF-κB pathways, as well as modulating the apoptotic mechanisms in cancer cells, making them more resistant to oxidative stress and apoptosis." (PMID 37623834, 2023). "Reportedly, the abrogation of metabolic activity triggered by the aberrant activation of the PI3K/AKT/mTOR pathway in cancer cells may result in the deregulation of genes involved in DNA damage and immune response, including DNA damage inducible transcript 4 (DDIT4)." (PMID 37391802, 2023). "Furthermore, using novel mTOR kinase inhibitors to treat cancer may result in cardiotoxicity in patients." (PMID 37115449, 2023). "At final, we also discovered that these hub genes may participate in the onset and progression of GC via the following cancer-associated pathways, namely, cell cycle, EMT, apoptosis, RAS/MAPK, PI3K/AKT, TSC/mTOR, hormone AR signaling, hormone ER signaling, as well as RTK." (PMID 37768204, 2023). "In addition, gain of function of CXXC5 induced inhibition of target genes, such as TSC1, and regulated the mTOR pathway positively, which could regulate the expression of PD-L1 in cancer cells." (PMID 36539038, 2023).